ENSG00000288529 (novel protein)
Synonyms: LOC128092253
Gene: Protein-coding gene on chromosome 6 (133,953,304 to 133,980,088, forward strand). Ensembl gene ENSG00000288529.
Genetic constraint (gnomAD): Missense variants: 0 observed, 0.32 expected, observed/expected ratio (o/e) 0, 90% interval 0 to 1.86.